CAV1 (caveolin 1)
Diseases named in the same sentence as CAV1 in open-access papers (continued):
Sharing a sentence is not in itself a finding about the gene and the disease.
hepatocellular carcinoma (continued). "Alternatively, others found that the presence of CAV1 in highly metastatic hepatocellular carcinoma cell lines not only promotes cell proliferation, angiogenesis, and migration but also inhibits autophagy." (PMID 32458269, 2020). "Our results show that exogenous ChoPlas-induced caveolin-1 overexpression can reduce pAkt levels in hepatoma cells, consistent with two previous studies which found that down-regulation of the PI3K/Akt pathway in caveolin-1 overexpressing cells sensitizes them to apoptotic stimuli." (PMID 24143228, 2013). "Furthermore, natural ChoPlas inhibited hepatoma cell proliferation via the PI3K/Akt pathway and was dependent on caveolin-1 activation, thus presenting natural ChoPlas as a potential cancer drug candidate." (PMID 24143228, 2013). "We also examined the methylation status in SMMC-7721 hepatoma cells and found that the caveolin-1 promoter was not methylated in mock-treated cells, whereas HBx-transfected cells were positive for both methylation and non-methylation." (PMID 22894556, 2012). "This study analyzes whether and how CAV1 is involved in the cytotoxic and pro-apoptotic actions of RES in a human hepatocellular carcinoma (HCC) model." (PMID 19321006, 2009). "Caveolin-1 (Cav-1), a structural and signaling protein on the cytoplasmic membrane, plays vital roles in various liver diseases, including a spectrum of conditions such as alcoholic fatty liver disease, NAFLD, fibrosis, liver cirrhosis, and hepatocellular carcinoma." (PMID 37941054, 2023). "A study reported activation of the PI3K/Akt pathway and the RAF/MEK/ERK pathway through caveolin 1 induced overexpression of IGF1R, thus promoting anchorage independence of hepatocellular carcinoma (HCC)." (PMID 33854965, 2021). "We addressed caveolin-1 and flotillin-1 expression in 90 human hepatocellular carcinoma (HCC) and adjacent noncancerous tissues (ANT) samples by SDS-PAGE and immunoblotting with specific antibodies." (PMID 25243186, 2014).
diabetes (66 papers, 2008 to 2026). "CAV1 deficiency significantly attenuated diabetes-induced cardiac systolic dysfunction and myocardial injury, and that cardiac-specific overexpression of CAV1 accelerated the progression of DCM." (PMID 40303344, 2025). "CAV1 deficiency significantly alleviated diabetes-induced myocardial hypertrophy, fibrosis, abnormal mitochondria, excessive reactive oxygen species production, and ferroptosis." (PMID 40303344, 2025). "Wheat germ agglutinin (WGA) staining showed that diabetes caused cardiomyocyte hypertrophy in WT mice, and the cross-sectional area of cardiomyocytes in CAV1-KO diabetic mice was smaller than that in WT diabetic mice." (PMID 40303344, 2025). "CAV1 deficiency significantly attenuated diabetes-induced myocardial hypertrophy, fibrosis, oxidative stress, and cardiomyocyte ferroptosis and improved cardiac dysfunction by activating the NRF2/GCLC signaling pathway." (PMID 40303344, 2025). "Cardiac functional tests revealed that ML385 reversed the protective effects of CAV1 deficiency in diabetes-induced cardiac dysfunction, as reflected by decreased EF and FS." (PMID 40303344, 2025). "Conversely, cardiac-specific overexpression of CAV1 exacerbated cardiac dysfunction and myocardial histological abnormalities caused by diabetes." (PMID 40303344, 2025). "MYH9, ERBB2, TCF4, VIM (vimentin), LRRK2 and CAV1 have been implicated as a principal mediator of diabetes mellitus." (PMID 36837510, 2023). "The results of recent investigations indicate that CAV-1 plays an important role in the association between diabetes and dementia." (PMID 35468852, 2022). "Little is known about CAV1 regulation in adipocytes; single nucleotide polymorphisms (SNPs) in the CAV1 gene have been associated with metabolic syndrome (MetS), which is a major risk factor for diabetes and coronary artery disease." (PMID 36497195, 2022). "As has been explored in preceding studies, CAV1 gene variants were correlated with IR, dyslipidemia, diabetes mellitus, and metabolic syndrome." (PMID 34001235, 2021). "CAV1 SNP variants have been suggested to be linked to metabolic syndrome (MetS), a major risk factor for diabetes and coronary artery disease." (PMID 32082483, 2020). "Cav-1 deficiency and gene variants are associated with insulin resistance, diabetes, and the hallmarks of the metabolic syndrome." (PMID 31534971, 2019). "Knockdown experiments of Cav-1 have been shown to cause cardiohypertrophy, diabetes, and pulmonary and focal cerebral ischemia and reperfusion injury." (PMID 28346478, 2017). "In addition, CAV1 has been shown to alleviate diabetes-associated cognitive impairment by modulating ferroptosis." (PMID 40180904, 2025). "CAV1 deficiency significantly improves diabetes-induced myocardial injury and cardiac dysfunction." (PMID 40303344, 2025). "Caveolin-1 (Cav-1) regulates the mitochondrial fission-mitophagy axis to maintain mitochondrial quality, thereby alleviating neuronal ferroptosis and significantly improving diabetes-associated cognitive dysfunction (DACD)." (PMID 39416788, 2024). "Additionally, DPP-4i restricted diabetes-associated cognitive deficits by modulating neuroinflammatory indicators of caveolin 1 (Cav 1) and brain-derived neurotrophic factor (BDNF), thus reducing inflammatory response in the brain." (PMID 38082288, 2023). "Caveolin-1 (CAV1) is implicated in the pathophysiology of diabetes and obesity." (PMID 36497195, 2022). "The association between Cav‐1 and eNOS was crucial in vascular homeostasis when confronted with oxidative stress, which was found in several disease states including atherosclerosis, diabetes, and myocardial infarction." (PMID 32508059, 2020). "Many cardiovascular risk factors such as diabetes mellitus, hypertension and hyperlipidemia are demonstrated to stimulate the interaction of Cav-1 and eNOS, reduce nitric oxide production resulting in endothelial dysfunction and subsequently the formation of atherosclerotic lesion." (PMID 33051481, 2020).
diabetes (continued). "The caveolin-1-null mice showed several metabolic/endocrine disorders that could have influenced their NP phenotype (e.g., insulin resistance leading to diabetes mellitus, which has been associated with premature NC senescence and apoptosis)." (PMID 26939667, 2016). "In addition to its role in normal cellular function, alterations in Cav1 expression and function are implicated in several pathophysiological conditions, such as inflammation, cancer, cardiovascular diseases, and diabetes." (PMID 39684412, 2024). "Our findings would provide valuable clues for developing novel treatments based on Cav-1 inhibition against diabetes under lipotoxicity." (PMID 42031171, 2026). "We showed that inhibition of CAV1 alleviated diabetes-induced myocardial injury by activating NRF2/GCLC signaling." (PMID 40303344, 2025). "Cardiac-specific CAV1 overexpression further aggravated diabetes-induced cardiac dysfunction, as indicated by decreased EF and FS." (PMID 40303344, 2025). "The regulation of autophagy and Cav-1 plays a certain role in endocrine diseases such as Hashimoto’s thyroiditis, diabetes, congenital lipodystrophy and abnormal fat metabolism." (PMID 41030451, 2025). "Mounting evidence points to malfunction in Cav-1 as a contributor to endothelial dysfunction in diabetes since increased expression of Cav-1 leads to a reduced EDR by impairing NO bioavailability." (PMID 38664801, 2024). "Several lines of evidence indicate the role of CAV1 in insulin secretion and insulin signaling in diabetes and metabolic syndrome." (PMID 39464889, 2024). "Blocking the binding of Cav-1 to eNOS provides atheroprotection in diabetes-accelerated atherosclerosis." (PMID 38664801, 2024). "Increased CaV1.2E9* channels are found in diabetic heart, which is attributed by AGEs-induced downregulation of Rbfox2, and hyperpolarized window current of CaV1.2E9* channels make it easier to be opened at the potentials closer to resting membrane potential." (PMID 37415128, 2023). "In diabetes mellitus, Caveolin-1 regulates insulin signal transduction and reduces inflammation and oxidative stress in diabetic complications." (PMID 36289445, 2023). "In order to further elucidate the molecular mechanisms underlying the memory enhancing effect of novel adamantane derivatives and DPP4 inhibitors, we have examined the gene expression levels of Bdnf and Cav1 in the hippocampal tissues of diabetes mice." (PMID 35468904, 2022). "We demonstrated that the overexpression of GLP-1-glucagon-like peptide as well as Bdnf, Cav1 genes translate into central blockade of pro-inflammatory synthesis of cytokines and significantly improvement on memory performance in diabetes mice." (PMID 35468904, 2022). "For example, it has been shown that CAV1 is a relevant protein in sex hormone-dependent modulation of different pathways, for example, malignant tumors, obesity, and diabetes mellitus type 2." (PMID 35059043, 2022). "In pancreatic β-cells, CAV1 plays a role in insulin receptor-mediated signaling, insulin secretion, and probably in diabetes." (PMID 34001235, 2021). "Cav1 has exerted its effect on insulin signaling and lipid metabolism within the liver, adipose tissues, and skeletal muscles to influence diabetes development." (PMID 34394002, 2021). "Angiogenesis is impaired in diabetes; CAV1-null mice fail to recover functional vasculature in hindlimbs after induced ischemia." (PMID 32082483, 2020). "In pancreatic β-cells, CAV1 plays a role in insulin receptor- (IR-) mediated signaling, insulin secretion, and possibly in diabetes." (PMID 32082483, 2020). "Our previous results and others showed that CAV1 expression level increases in diabetes, oxidative stress, and senescent cells." (PMID 32082483, 2020).
diabetes (continued). "In contrast, delayed wound healing in diabetes is connected with overexpression of Cav-1, induced by oxidative stress, which leads to the development of the cellular senescence." (PMID 31877626, 2019). "An association between leptin and CAV-1 has been provided, suggesting an important role for CAV-1 in obesity and type 2 diabetes mellitus development." (PMID 31500090, 2019). "Delayed wound healing in diabetes is connected with substantial overexpression of Cav-1 and induction of cellular senescence in dermal fibroblasts, whereas suppression of Cav-1 ameliorated both premature senescence and impaired wound healing." (PMID 31877626, 2019). "According to our data, the first-line diabetes drug metformin elicited induction of caveolin-1 in BT-474 cells, peaking at around 24 to 48 hours." (PMID 29500444, 2018). "In this study, diabetes drug metformin was investigated in terms of induction of caveolin-1 expression for increased efficacy of subsequent T-DM1 application." (PMID 29500444, 2018). "The process leads to the phosphorylation of Cav-1 tyrosine 14 mediated by c-Abl, which facilitates the trafficking of the receptor into relatively cav1-enriched lipid rafts and contributes to the Ang II-related BK channel dysfunction in diabetes." (PMID 28955251, 2017). "Recently, it has been reported that CAV1 is an important target protein in sex hormone-dependent regulation of various metabolic pathways, particularly in cancer and diabetes." (PMID 24608114, 2014). "This strategy has the potential to improve endothelial dysfunction by upregulating eNOS activity in diabetes and cardiovascular disease, both of which have impaired Cav-1/eNOS signaling." (PMID 22013533, 2012). "From this diabetic nephropathy sub-network module we have proposed the two putative interactions of PTPN1 with EGFR and CAV1 which have been highlighted for the first time in diabetes condition." (PMID 19997558, 2009). "While these strategies remain speculative, further elucidation of Cav-1’s role in insulin signaling may pave the way for novel therapeutic approaches to diabetes and related metabolic disorders." (PMID 40243482, 2025). "In the mouse diabetes model, it has been found that high glucose reduces the transfer of Sirtuin 6 (Sirt6) from the nucleus to the cytoplasm, leading to an increase in the acetylation level of Cav-1." (PMID 41030451, 2025). "As HG could depolarize the membrane potential of VSMCs, this may further augment the functions of vascular CaV1.2 channels due to the upregulated CaV1.2E9*,ΔE33 isoforms in diabetes." (PMID 38575795, 2024). "AGEs accelerate the development of diabetes-related AS by increasing the LDL transcytosis in ECs through the activation of the RAGE/NF-κB/Caveolin-1 axis, which may be targeted to prevent or treat diabetic macrovascular complications." (PMID 37605109, 2023). "The results of our research were consistent with the observations of other scientists, we indicated that diabetes mice receiving daily for 14 days novel adamantane derivative 2 exhibited significantly higher expression level of hippocampal Cav1 and the reduction of memory and learning impairments." (PMID 35468904, 2022). "Senescent dermal fibroblasts induced by diabetes show CAV-1 upregulation, which may be due to oxidative stress, while inhibition of CAV-1 prevents diabetes- and oxidative stress-induced premature senescence and enhances wound healing." (PMID 36532050, 2022). "It is demonstrated that another variant of the CAV1 gene means rs926198 is linked to dyslipidemia, particularly low HDL cholesterol and also other metabolic disorders, including diabetes, insulin resistance, metabolic syndrome, and cardiovascular risk in Caucasians and Hispanics." (PMID 34544501, 2021). "Besides, Cav1 has exerted its effect on insulin signaling and lipid metabolism within the liver, adipose tissues, and skeletal muscles to influence diabetes development." (PMID 34394002, 2021).
diabetes (continued). "Here, we summarize the recent progress on the role of CAV1 in diabetes and diabetic complications." (PMID 32082483, 2020). "Diseases such as obesity and diabetes could also provide an avenue through which molecular clues on the involvement of CAV1 in cellular metabolism can be unraveled for subsequent investigation in cancer." (PMID 27852311, 2016). "The absence of caveolae (initiated by caveolin-1 (cav-1) knock-down or gene ablation) caused disaggregation of the Ang II-BK channel signaling cascade and preserved BK channel function in diabetes." (PMID 26287261, 2015). "In addition, Caveolin-1 was also found to be upregulated in rat diabetic retina." (PMID 36289445, 2023). "Moreover, a one-way analysis of variance with Tukey’s post hoc test showed that diabetes suppresses the expression of the Cav1 gene in the hippocampus and the prefrontal cortex of mice, which correlates with the results of behavioral research described earlier and those presented in this paper." (PMID 35628311, 2022). "However, whether the changes of Cav-1 in other organs of patients with type 2 diabetes will affect other signaling proteins to regulate the progression of diabetes is worthy of further investigation." (PMID 34955837, 2021). "Studies have revealed that Cav1 or lipid rafts are implicated in neurodegenerative diseases such as Alzheimer’s disease (AD) and Parkinson’s disease (PD), and that Cav1 is also involved in non-neural diseases such as cancer and diabetes." (PMID 33726791, 2021). "However, whether caveolin-1 is related to diabetes-induced CD147 glycosylation in the central nervous system has not been reported." (PMID 30953513, 2019). "Therefore, Cav-1 is a potential therapeutic target for diabetes-induced cognitive dysfunction." (PMID 28489581, 2017). "Bonds and colleagues explored the relationship between type 2 diabetes mellitus (T2DM) and AD, finding reduced Cav-1 levels in both the brains of T2DM patients and in diabetic mouse models." (PMID 40243482, 2025). "Silencing Cav-1 and upregulating ZNRF1 were sufficient to improve EDR of diabetic aortas, while overexpression of Cav-1 and downregulation of ZNRF1 abolished the effects of NCEH1 on endothelial function in diabetes." (PMID 38664801, 2024). "Therefore, CAV1 might be an effective therapeutic target for diabetes-related cognitive decline." (PMID 32082483, 2020). "The expression pattern of CAV1 was similar to that of DPP-4 and integrin β1 (increased by the BSA injection and diabetes and decreased by the TENE treatment)." (PMID 31101909, 2019). "Recently, it has been reported that CAV1 is an important target protein in E2- as well as DHT-dependent regulation of various metabolic pathways, particularly in cancer and diabetes." (PMID 24608114, 2014). "Caveolin-1 (CAV1), a membrane protein that is necessary for the formation and maintenance of caveolae, is a promising drug target for the therapy of various diseases, such as cancer, diabetes, and liver fibrosis." (PMID 34684779, 2021). "For instance, in pathological conditions such as diabetes, ischemia, or inflammation, disruptions in cellular metabolism could impair the activity of RNF213 and its ability to regulate Cav-1, leading to endothelial dysfunction and promoting vascular abnormalities." (PMID 40497951, 2025). "CAV1 expression in adipose tissues (AT) is augmented in obese individuals with or without diabetes." (PMID 36497195, 2022). "Expression of either calmodulin (CaM) or caveolin-1 was not affected by diabetes." (PMID 30886586, 2019).
diabetes (continued). "Additionally, the persistent exposure of diabetic cells to high glucose concentrations (25 mM) promoted the upregulation of caveolin-1, N-cadherin, SIRT3, SIRT7 and lactate levels, suggesting that long-term diabetes may promote cell proliferation." (PMID 30093732, 2018). "Although a definite role for Cav-1 in diabetes has not been fully elucidated, it is apparent that modulating eNOS function by Cav-1 could be beneficial in ameliorating diabetes mediated endothelial dysfunction." (PMID 22013533, 2012). "In addition, Cav-1 can upregulate the expression of SGLT1, indicating that Cav-1 may play a key role in glucose uptake by renal tubules, but the role of blood glucose in diabetes may need to be studied in the future." (PMID 34955837, 2021).